NAP1L1 (nucleosome assembly protein 1 like 1)
Diseases named in the same sentence as NAP1L1 in open-access papers (continued):
Sharing a sentence is not in itself a finding about the gene and the disease.
glioma (continued). "The MTT assay demonstrated that NAP1L1 knockdown could significantly decrease the glioma cells proliferation as compared to that of the control (si-NC) group." (PMID 34959221, 2021). "In summary, NAP1L1 could promote proliferation and chemoresistance in glioma cells by interacting with HDGF and activating c-Jun to induce the expressions of CCND1/CDK4/CDK6." (PMID 34959221, 2021). "Interestingly, glioma cells with stably silenced NAP1L1 also significantly inhibited the proliferation." (PMID 34959221, 2021). "Thus, NAP1L1 has the potential to be a promising biomarker as well as therapeutic target for the pathogenesis of glioma." (PMID 34959221, 2021). "Functional studies suggested that knocking down NAP1L1 could significantly inhibit glioma cell proliferation both in vitro and in vivo, as well as enhance the sensitivity of glioma cells to cisplatin (cDDP) in vitro." (PMID 34959221, 2021). "High expression of NAP1L1 in glioma tissues indicated shorter overall survival in glioma patients." (PMID 34959221, 2021). "HDGF knockdown in NAP1L1-overexpressing glioma cells significantly inhibited cell proliferation." (PMID 34959221, 2021). "Furthermore, univariate and multivariate cox regression analyses showed that NAP1L1 was a disadvantage predictive factor, which indicated poor survival in glioma patients." (PMID 34959221, 2021). "Moreover, NUCL, TRIM28, VIM, and NAP1L1 were indicated as good markers to distinguish glioma tissues from reference tissues." (PMID 28498803, 2017). "Additionally, to clarify how NAP1L1 promotes the proliferation of glioma cells, we attempted to determine whether there is a direct relationship between NAP1L1 and c-Myc." (PMID 37770914, 2023). "In addition, NAP1L1 overexpression could upregulate HDGF expression in glioma cells, while NAP1L1 knockdown decreased the protein level expression of HDGF." (PMID 34959221, 2021). "Upregulation of NAP1L1 increased its binding with c-Myc and activated c-Myc, which induced the expression of CCND1/CDK4, promoting glioma cell temozolomide resistance and proliferation." (PMID 37770914, 2023). "The upregulation of NAP1L1 increased its binding with c-Myc and thereby activated c-Myc, inducing the expression of CCND1/CDK4 and thereby promoting glioma cell temozolomide resistance and proliferation." (PMID 37770914, 2023). "To further evaluate the relationship between HDGF and NAP1L1, we performed MTT and EdU assays using NAP1L1-overexpressing glioma cells upon HDGF knockdown." (PMID 34959221, 2021). "To verify the functions of NAP1L1 and HDGF, we analyzed the correlation of NAP1L1 and HDGF expressions with widely recognized clinicopathological parameters in glioma specimens." (PMID 34959221, 2021). "The high expressions of NAP1L1 or/and HDGF in glioma tissues indicate shorter overall survival in glioma patients." (PMID 34959221, 2021). "Glioma cells were processed with various concentrations of DDP after 48 h and the cell growth inhibition rates were calculated after NAP1L1 silencing." (PMID 34959221, 2021). "Correlation analysis indicated a significantly positive correlation between NAP1L1 and HDGF expressions in glioma tissues (r = 0.279, P = 0.003)." (PMID 34959221, 2021). "Immunohistochemistry indicated that NAP1L1 and hepatoma-derived growth factor (HDGF) were enhanced in glioma as compared to the para-tumor tissues." (PMID 34959221, 2021). "To determine the role of NAP1L1 and HDGF in glioma, we analysed the protein level expressions of NAP1L1 and HDGF by immunostaining in 108 glioma tissues and 24 para-tumor tissues." (PMID 34959221, 2021). "We demonstrate the potential use of NAP1L1, NUCL, CRMP1, ACTB, and VIM for differentiation between glioblastoma and lower grade gliomas, with DPYSL2 as a promising “glioma versus reference” biomarker." (PMID 28498803, 2017).
glioma (continued). "Bioinformatic analysis of genes of interest against TCGA RNA sequencing data proposed TRIM28, VIM, NAP1L1 and DPYSL2 as promising “glioma versus reference” biomarkers, and suggested CRMP1, NAP1L1, NUCL, ACTB and VIM for discrimination between GBM and LGG." (PMID 28498803, 2017). "The upregulation of NAP1L1 increased its binding with c-Myc and, further, activated c-Myc, which induced the expression of CCND1/CDK4 and thereby promoted the resistance to temozolomide and proliferation of glioma cells." (PMID 37770914, 2023). "To further clarify the role of MYH9 and NAP1L1 in glioma, we attempted to determine whether MYH9 participates in regulating the expression of NAP1L1." (PMID 37770914, 2023). "Correlation between NAP1L1 and HDGF expression in glioma tissues." (PMID 34959221, 2021). "Next, the prognostic implications of NAP1L1 and HDGF in gliomas were assessed." (PMID 34959221, 2021). "Analysis of OS and disease free survival (DFS) showed that overexpression of NAP1L1 was a negative factor that decreased the overall survival duration in glioma patients." (PMID 34959221, 2021). "To study the potential role of NAP1L1 in the progression of glioma, we transfected LN229 and U87 cells with lentiviral constructs expressing short hairpin RNA targeting NAP1L1 and the corresponding negative control (shNC)." (PMID 34959221, 2021).
gastric cancer (5 papers, 2016 to 2022). A primary or metastatic malignant neoplasm involving the stomach. "Some of the proposed genes have also been implicated in other cancers, for example gastric cancer (vimentin), large B-cell lymphoma (nucleolin), and pancreatic cancer (NAP1L1)." (PMID 33187334, 2020). "Although many studies have discussed the importance of NAP1L1, its role in hyperglycemia-induced proliferation and migration of gastric cancer cells remains undocumented." (PMID 35461311, 2022). "Functional analysis of TRIM28, EIF4A2, NAP1L1, PLD3, RPL18A, and TRPM7 suggested that they play direct roles in gastric cancer." (PMID 27835598, 2016). "Furthermore, lncRNA SNHG8 modulated several functional genes, including TRIM28, NAP1L1 and TRPM7 which affected downstream cancer pathways in gastric cancer." (PMID 30299268, 2018). "Moreover, some studies have shown that miRNA-2 promoted carcinogenic activity by upregulating the expression of RAN in HCC cells; the high expression of HNRNPA1 promoted the invasion of gastric cancer cells; lncRNA CDKN2B-AS1 promoted the growth of HCC by regulating the let-7c-5p/NAP1L1 axis." (PMID 34426790, 2021).
lung adenocarcinoma (5 papers, 2021 to 2025). A carcinoma that arises from the lung and is characterized by the presence of malignant glandular epithelial cells. "In lung adenocarcinoma (AC) derived A549 cells, NAP1L1 regulates the NF-κB signaling pathway by modifying gene expression of the anti-apoptotic factor Mc1-1." (PMID 35351053, 2022).
renal carcinoma (5 papers, 2018 to 2022). A carcinoma arising from the epithelium of the renal parenchyma or the renal pelvis. "We went on to examine the correlation of KRAS and NAP1L1 with miR-532-5p in 20 renal cancer tissues." (PMID 30082686, 2018). "NAP1L1 participates in the miR-532-5p-mediated suppression of renal cancer cell proliferation." (PMID 34368121, 2021).
breast carcinoma (4 papers, 2021 to 2024). "Consistent with the prediction, immunohistochemistry staining showed that NAP1L1 protein expression was significantly increased in breast cancer tissues." (PMID 34774047, 2021). "After transiently or stably suppressing NAP1L1 expression in breast cancer cells by respectively using siRNA or lentivirus-mediated shRNA, it was observed that the ability of cell proliferation and EDU staining was significantly reduced in vitro." (PMID 34774047, 2021). "A bioinformatics analysis was conducted to determine the differential expression of NAP1L1 in breast cancer and find the potential biomarker that interacts with NAP1L1 and hepatoma-derived growth factor (HDGF)." (PMID 34774047, 2021). "To investigate the possible role of NAP1L1 in breast cancer, we first observed that the expression of NAP1L1 protein was significantly upregulated in breast cancer tissues compared to normal breast tissues based on the CPTAC database." (PMID 34774047, 2021). "Stably or transiently knocking down NAP1L1 reduced the cell growth in vivo and in vitro via repressing the cell cycle signal in breast cancer." (PMID 34774047, 2021). "Here, we also examined the protein expression of Caspase3 and Caspase9 and found their upregulated expression in NAP1L1-knocking down breast cancer cells." (PMID 34774047, 2021). "Our data demonstrated that NAP1L1 functions as a potential oncogene via interacting with HDGF to recruit c-Jun in breast cancer." (PMID 34774047, 2021). "Further, immunochemistry was used to detect the expression of NAP1L1 protein in breast cancer tissues and normal breast tissues." (PMID 34774047, 2021). "Subsequently, A tissue microarray (TMA) containing 97 breast cancer tissue samples and 10 paracarcinoma tissues was used to perform NAP1L1 expression level, and cell staining scores were used to determine low and high expression." (PMID 34774047, 2021). "In vivo experiment showed that the ability of subcutaneous tumor formation of breast cancer cells significantly decreased after the expression of NAP1L1 was stably inhibited." (PMID 34774047, 2021). "To explore the possible role of NAP1L1 in breast cancer, we first examined NAP1L1 expression and its correlation with clinical feature and survival prognosis in breast cancer." (PMID 34774047, 2021). "The data show that the NAP1L1 mRNA and protein levels were significantly downregulated in NAP1L1-knocking down breast cancer cells." (PMID 34774047, 2021). "Taken together, an increased NAP1L1 protein level is an unfavorable outcome for breast cancer patients." (PMID 34774047, 2021). "The data showed that overexpressed NAP1L1 as an unfavorable factor that reduced the overall survival time of breast cancer patients." (PMID 34774047, 2021). "These detailed data indicate NAP1L1 as a potential oncogene, significantly participating in the pathogenesis of breast cancer." (PMID 34774047, 2021). "Here, NAP1L1 protein was found to be upregulated and considered as an unfavorable factor for the poor progression and prognosis of breast cancer patients." (PMID 34774047, 2021). "Expression of NAP1L1 (nucleosome assembly protein 1-like 1) is significantly upregulated in tumor tissues compared with adjacent nontumor tissues in many cancers, including liver, colon, ovarian, breast cancer, etc.." (PMID 36980210, 2023). "Furthermore, the cell proliferation ability was also restored in NAP1L1-suppressed breast cancer cells." (PMID 34774047, 2021). "Furthermore, coimmunoprecipitation (Co-IP) assay and confocal microscopy were performed to explore the detailed molecular mechanism of NAP1L1 in breast cancer." (PMID 34774047, 2021). "Here, we also investigated the role of NAP1L1 in breast cancer cell growth." (PMID 34774047, 2021). "Finally, multivariable analysis demonstrated that increased NAP1L1 expression is an independent prognosis marker for the overall survival in breast cancer." (PMID 34774047, 2021).
breast carcinoma (continued). "Furthermore, we also observed that knocking down NAP1L1 upregulated the expression of Caspase3 and Caspase9 protein levels, indicating that increased cytotoxicity is also involved in tumor suppression in NAP1L1 knocking down breast cancer cells." (PMID 34774047, 2021). "Here, NAP1L1 was found to combine with HDGF by Co-IP examination in breast cancer cells." (PMID 34774047, 2021). "The data show a significant elevation of NAP1L1 protein expression in breast cancer tissues." (PMID 34774047, 2021). "Here, we tried to use CoIP to confirm the interaction of HDGF with NAP1L1 in breast cancer." (PMID 34774047, 2021). "Furthermore, the ability of cell proliferation and EdU staining was restored in vitro in NAP1L1-suppressing breast cancer cells." (PMID 34774047, 2021). "Furthermore, an increase in NAP1L1 protein expression was found to be a predictor for poor survival prognosis in the high NAP1L1 expression group compared with the low expression group in breast cancer patients." (PMID 34774047, 2021). "However, the molecular basis of NAP1L1 in breast cancer is still unclear." (PMID 34774047, 2021). "The confocal microscopic images showed the colocalization of NAP1L1 and HDGF in the cytoplasm of breast cancer cells." (PMID 34774047, 2021). "The role and molecular mechanism of Nucleosome Assembly Protein 1 Like 1 (NAP1L1) in breast cancer have not been reported." (PMID 34774047, 2021). "The average weight and volume of tumors significantly decreased in the xenograft mice after the injection of NAP1L1-decreasing breast cancer cells compared with the negative control group." (PMID 34774047, 2021). "NAP1L1 interacted with the HDGF, an oncogenic factor for tumors, and the latter subsequently recruited the key oncogenic transcription factor c-Jun, which finally induced the expression of cell cycle promoter Cyclin D1(CCND1) and thus the cell growth of breast cancer." (PMID 34774047, 2021). "Yet, the role and molecular mechanism of NAP1L1 in breast cancer have not been reported." (PMID 34774047, 2021). "Furthermore, NAP1L1 was observed to be an interaction factor of HDGF, recruiting the key oncogenic transcription factor c-Jun and thus inducing the expression of cell cycle promoter CCND1, which finally stimulated breast cancer proliferation." (PMID 34774047, 2021). "However, the role and molecular basis of NAP1L1 in breast cancer have never been documented." (PMID 34774047, 2021). "Among the 4 candidate proteins, UBE2O has been proved to bind to NAP1L1 and promote EMT in head and neck squamous cell carcinoma and breast cancer, but the relationship between UBE2O and NAP1L1 and EMT in HCC has not been studied." (PMID 38816735, 2024). "In breast cancer, UBE2O promoted EMT through the UBE2O/AMPKα2/mTORC1 axis, but the relationship between UBE2O and NAP1L1 and EMT in HCC has not been studied." (PMID 38816735, 2024).
ovarian carcinoma (4 papers, 2014 to 2025). A malignant neoplasm originating from the surface ovarian epithelium. "To explore the correlation between NAP1L1 expression and survival in OC patients, we analyzed tumor tissues obtained from 149 patients with ovarian cancer using IHC." (PMID 35351053, 2022). "In this study, we suggest the potential of NAP1L1 as a prognostic biomarker and therapeutic target for the treatment of ovarian cancer (OC)." (PMID 35351053, 2022). "We found that NAP1L1 expression staining was located within the cytoplasm and NAP1L1 overexpression was detected in epithelial ovarian cancer tissues with IHC." (PMID 35351053, 2022). "Deregulation of NAP1L1 expression has been documented for several tumors such as small intestine carcinoid neoplasia, neuroendocrine tumors, ovarian cancer and hepatoblastomas." (PMID 24401680, 2014). "NAP1L1 is involved in the ovarian cancer cell response to cytotoxic gold compounds." (PMID 34959221, 2021).
endometrial carcinoma (3 papers, 2021 to 2022). A malignant tumor arising from the epithelium that lines the cavity of the uterine body. "Prior investigation performed by our group using mass spectrometry (unpublished data) had determined that NAP1L1 was a potential candidate interaction protein of HDGF in endometrial carcinoma." (PMID 35351053, 2022). "Prior investigation from our group using mass spectrometry combined with exogenous co-IP, indicated that HDGF was a potential interacting partner of NAP1L1 in endometrial carcinoma (unpublished data)." (PMID 34959221, 2021). "Interestingly, a previous study in our group had found that NAP1L1 is a potential candidate of HDGF interaction proteins in endometrial carcinoma using exogenous Co-IP combined with mass spectrometry (unpublished data)." (PMID 34368121, 2021). "Interestingly, previous studies in our lab had found that NAP1L1 is a potential candidate of HDGF interaction proteins in endometrial carcinoma using exogenous Co-IP assay combined with mass spectrometry (unpublished data)." (PMID 34368121, 2021). "In our preliminary work, using mass spectrometry, we predicted a direct interaction between NAP1L1 and HDGF proteins, and this was confirmed in endometrial carcinoma (unpublished data)." (PMID 34959221, 2021).
fibrosis (3 papers, 2023 to 2025). the formation of excess fibrous connective tissue in an organ or tissue in a reparative or reactive process. "Myocardial fibrosis scores were heightened in C0 NAP1L1+ TCs (stage I), C1 CA2+ TCs (stage 0), C1 CA2+ TCs (stage I), and C0 NAP1L1+ TCs (stage II)." (PMID 40842994, 2025). "We demonstrated that NAP1L1 is a profibrotic factor that inhibits YAP1 ubiquitination and degradation to regulate cardiac fibrosis." (PMID 37593048, 2023).
cardiac hypertrophy (2 papers, 2025). "Here we show that the somatic variant NAP1L1 p.D349E was involved in cardiac hypertrophy in sporadic HCM patients." (PMID 40169585, 2025). "Through phalloidin staining, we found that Nap1l1 p.D349E caused a significant increase in the cell surface area (CSA) of cardiomyocytes, which was consistent with the cardiac hypertrophy phenotype of HCM patients." (PMID 40169585, 2025). "Compared with those in the control mice, both C-176 and IFNAR1 antibody treatment prevented Nap1l1 p.D349E-mediated cardiac hypertrophy and fibrosis." (PMID 40169585, 2025). "We further investigated whether cGAS-Sting signaling was involved in Nap1l1 p.D349E-mediated cardiac hypertrophy." (PMID 40169585, 2025). "In response to excess interferon in the matrix, cells without NAP1L1 p.D349E and cardiomyocytes with NAP1L1 p.D349E cooperate to promote cardiac hypertrophy." (PMID 40169585, 2025).
cardiomyopathy (2 papers, 2025). A disease of the heart muscle or myocardium proper. "In conclusion, this work redefines Wnt2 as a master regulator of I/R injury through Nap1L1-mediated transcriptional reprogramming, providing a mechanistic foundation for targeting redox dysregulation and multiple forms of cell death in post-I/R cardiomyopathy." (PMID 41397965, 2025). "Future studies exploring the role of NAP1L1 in cardiac fibroblasts, as well as the crosstalk between cardiomyocytes and fibroblasts, could provide valuable insights into the broader impact of the NAP1L1 p.D349E variant in HCM and other forms of cardiomyopathy." (PMID 40169585, 2025).
heart failure (2 papers, 2023 to 2025). Inability of the heart to pump blood at an adequate rate to meet tissue metabolic requirements. "Heart failure scores were elevated in C0 NAP1L1+ TCs (G1), C0 NAP1L1+ TCs (G2/M), C0 NAP1L1+ TCs (S), C2 MKI67+ TCs (G2/M), and C2 MKI67+ TCs (S)." (PMID 40842994, 2025). "The cardiac failure scores were significantly elevated in C0 NAP1L1+ TCs (stage II), C1 CA2+ TCs (stage II), and C2 MKI67+ TCs (stage II)." (PMID 40842994, 2025). "Moreover, our study identifies a pivotal role for NAP1L1 in myocardial fibrosis post injuries and inhibition of the function of NAP1L1 might be a therapeutic strategy for preventing heart failure." (PMID 37593048, 2023). "Violin plots illustrating inter-subpopulation disparities indicated that C0 NAP1L1+ TCs and C2 MKI67+ TCs possessed considerably elevated heart failure scores, whereas C1 CA2+ TCs demonstrated moderate values, and C3 ITLN1+ TCs displayed the lowest scores." (PMID 40842994, 2025). "We additionally illustrated the expression pattern and density of heart failure scores among subpopulations by UMAP plots, indicating that peak values are primarily concentrated in C0 NAP1L1+ TCs and C2 MKI67+ TCs." (PMID 40842994, 2025).
hepatoblastoma (2 papers, 2014 to 2016). Hepatoblastoma (HB) is a malignant hepatic tumor and is the most common pediatric liver cancer. "Nap1L1 is overexpressed in certain tumors such as hepatoblastoma and carcinoid of the small intestine." (PMID 27835598, 2016).